HAVCR1 (hepatitis A virus cellular receptor 1)
Description:
Phosphatidylserine receptor that plays an important functional role in regulatory B-cell homeostasis including generation, expansion and suppressor functions. Involved in efferocytosis, the process by which apoptotic cells are removed, by binding to phosphatidylserine present on apoptotic cells and promoting their engulfment. Confers phagocytic ability on injured kidney epithelial cells, allowing them to bind to and internalize apoptotic bodies and necrotic debris following kidney injury. The ectodomain binds to the surface of apoptotic kidney epithelial cells via phosphatidylserine and oxidized phospholipids exposed on the cell membrane of the apoptotic cells. HAVCR1-expressing cells are also capable of phagocytosing Gram-negative and Gram-positive bacteria. As P-selectin/SELPLG ligand, plays a specialized role in activated but not naive T-cell trafficking during inflammatory responses. Controls thereby T-cell accumulation in the inflamed central nervous system (CNS) and the induction of autoimmune disease. Acts as a regulator of T-cell proliferation (By similarity). Also regulates expression of various anti-inflammatory cytokines and co-inhibitory ligands including IL10 (By similarity). (Microbial infection) Acts as a receptor for Hepatitis A virus. (Microbial infection) Acts as a receptor for Ebolavirus and Marburg virus by binding exposed phosphatidyl-serine at the surface of virion membrane. Serves as a dual receptor for Ebolavirus by also interacting with envelope glycoprotein GP. (Microbial infection) Acts as a receptor for Dengue virus by binding exposed phosphatidyl-serine at the surface of virion membrane. TIM1 and Dengue virus are co-internalized during virus entry. (Microbial infection) Acts as a receptor for Zika virus by binding to envelope protein E. (Microbial infection) Plays a positive role in Chikungunya virus cell entry.
Synonyms: HAVcr-1; KIM-1; TIMD-1; TIM; TIM-1; CD365; KIM1; TIM1; TIMD1; HAVCR
Tractability: Antibody: UniProt places it where antibodies can reach, with high confidence; UniProt predicts a signal peptide or a membrane-spanning region; its Gene Ontology location is reachable by antibodies, with medium confidence. PROTAC: UniProt records ubiquitination sites on it; ubiquitination databases record sites on it.
Gene: Protein-coding gene on chromosome 5 (157,025,939 to 157,069,396, reverse strand). Ensembl gene ENSG00000113249.
Subcellular location: Cell membrane; Cell projection, phagocytic cup; Cytoplasmic vesicle, phagosome
Subcellular location (Human Protein Atlas): Vesicles
Pathways (Reactome):
Disease: Attachment and Entry; Dengue Virus Attachment and Entry
Gene Ontology:
Molecular function: phosphatidylserine binding; protein binding; virus receptor activity
Biological process: apoptotic cell clearance; phagocytosis, engulfment; positive regulation of mast cell activation; symbiont entry into host cell
Cellular component: motile cilium; plasma membrane; autophagosome membrane; cell surface; endosome membrane; phagocytic cup; phagocytic vesicle
Genetic constraint (gnomAD): Loss-of-function variants: 11 observed, 6.99 expected, observed/expected ratio (o/e) 1.57, 90% interval 0.94 to 1.94. That is too few expected variants to judge how well the gene tolerates losing a copy. Missense variants: 185 observed, 179.3 expected, observed/expected ratio (o/e) 1.03, 90% interval 0.92 to 1.17. Synonymous variants: 78 observed, 72.06 expected, observed/expected ratio (o/e) 1.08, 90% interval 0.9 to 1.31.
Homologues: Orthologues: chimpanzee HAVCR1 (87% identical), rat Timd2 (37% identical), mouse Havcr1 (37% identical), rat Havcr1 (36% identical), mouse Timd2 (30% identical), mouse Timd5 (23% identical), rat Havcr1l1 (22% identical), rat Havcr1l2 (20% identical), mouse Timd6 (18% identical), Caenorhabditis elegans T25B2.1 (6% identical), Caenorhabditis elegans T13C5.10 (4% identical), Caenorhabditis elegans T13C5.2 (4% identical), and 6 more. Paralogues in human: TIMD4 (27% identical), HAVCR2 (22% identical), MED7 (7% identical).
Diseases named in the same sentence as HAVCR1 in open-access papers:
HAVCR1 is named in the same sentence as 223 diseases in open-access papers, as found by Europe PMC text mining. Sharing a sentence is not in itself a finding about the gene and the disease. The quoted sentences say what the papers report.
acute kidney injury (294 papers, 2011 to 2026). Sudden and sustained deterioration of the kidney function characterized by decreased glomerular filtration rate, increased serum creatinine or oliguria. "Although HAVCR1 (KIM-1) and LCN2 (NGAL) have been characterized as sensitive markers of acute kidney injury, recent reports revealed that their kidney expression levels also increased in progressive renal disease." (PMID 26317775, 2015). "The mRNA expression of well-known acute kidney injury (AKI) biomarkers like LCN2 and HAVCR1/KIM-1 has been found to be significantly increased in recipients developing delayed graft function (DGF)." (PMID 26249165, 2015). "The expressions of Tgfb1 and Havcr1, which increased in acute kidney injury, did not change significantly." (PMID 35633893, 2022). "Despite the fact that kidney samples originated from patients without kidney injury, the PT_VCAM1 population showed increased expression of kidney injury molecule-1 (KIM1, HAVCR1), which is a biomarker that is increased in acute kidney injury and chronic kidney disease." (PMID 33850129, 2021). "This deficiency has also been shown in mice transitioning from acute kidney injury (AKI) to CKD, while upregulation of Havcr1 and Lcn2 act as early biomarkers for AKI." (PMID 40374849, 2025).
kidney damage (187 papers, 2011 to 2026). "Additionally, PT VCAM1 represents a distinct subset of PT cells with abnormal expression of VCAM1 and HAVCR1, which is a specific cell subset associated with kidney damage in DN patients." (PMID 38978780, 2024). "We evaluated the expression of kidney damage‐related genes (Havcr1, Lcn2, and Spp1) and found that MHY5396 treatment significantly reduced their expression in the kidneys." (PMID 41159141, 2025). "RT-qPCR detected elevated transcription levels of Lipocalin2 (LCN2; Lcn2) and Kidney injury molecule-1 (KIM-1;Havcr1) indicating kidney damage progressing over time." (PMID 39681572, 2024). "The well-known biomarker of kidney damage Havcr1, also known as kidney injury molecule-1 (KIM-1), is commonly elevated expression in AKI, renal trauma and kidney stone disease." (PMID 37208718, 2023). "Kidney injury molecule-1, encoded by HAVCR1, is a type 1 transmembrane protein that is undetectable in normal kidneys but is markedly upregulated after kidney damage." (PMID 35327386, 2022). "The expression of Havcr1 also tended to increase in tandem with kidney damage, although this relationship was not statistically significant." (PMID 26317775, 2015).
chronic kidney disease (112 papers, 2008 to 2026). Impairment of the renal function secondary to chronic kidney damage persisting for three or more months. "HAVCR1 expression in PT_VCAM1 suggests that PT_VCAM1 likely represents a subpopulation of proximal tubular cells that is undergoing injury in situ, and expands in aging and chronic kidney disease." (PMID 33850129, 2021). "Hepatitis A virus cellular receptor 1 (Havcr1, also known as Kim-1/Tim-1) and lipocalin 2 (Lcn2, also known as Ngal) are excellent markers to predict TILs in both AKI and chronic kidney disease (CKD)." (PMID 29109726, 2017).
kidney injury (76 papers, 2011 to 2026). Trauma to the kidney. "Candidate genes and/or their proteins such as HAVCR1 (KIM-1) and LCN2 (NGAL) in body fluids were also associated with kidney injury." (PMID 34276651, 2021). "We found that the protein SPP1, C3 and HAVCR1 might also play critical roles in the ER stress and phagocytosis in the CaOx crystal formation process and its related kidney injury." (PMID 36932340, 2023). "Furthermore, recurrent regulation of e.g. Havcr1 (KIM-1) and Lcn2 (NGAL) were found, indicating induced kidney injury at these absorbed doses (up to 140 MBq of injected activity)." (PMID 26287527, 2015).
Sepsis (65 papers, 2013 to 2026). Sepsis is defined as life-threatening organ dysfunction caused by a dysregulated host response to infection. "Known renal injury markers, such as markers Lcn2 (NGAL), Havcr1 (KIM1), Timp2, Igfbp7, are tubular injury markers and therefore are not indicative of the microvascular response in mouse CLP-sepsis." (PMID 40892345, 2025).
ischemia (32 papers, 2011 to 2026). A hypoperfusion of the BLOOD through an organ or tissue caused by a PATHOLOGIC CONSTRICTION or obstruction of its BLOOD VESSELS, or an absence of BLOOD CIRCULATION. "Also, the mildest ischemia-time condition (18 minutes of UIRI) induced a significant lower upregulation of Havcr1 expression as compared to the most severe condition (30 minutes of UIRI) at week 12 (p<0.05)." (PMID 27007127, 2016).
type 2 diabetes (27 papers, 2016 to 2025). "Through Mendelian randomization we demonstrate potentially causal effects of FGF21 and HAVCR1 on risk for type 2 diabetes, of HPGDS on BMI, and of OXT on risk for lacunar stroke." (PMID 40225784, 2025).
COVID-19 (23 papers, 2021 to 2026). A disease caused by infection with severe acute respiratory syndrome coronavirus 2. "The hepatitis A virus cellular receptor (HAVCR1, also called KIM1), used by Ebola, Marburg, Dengue, and Zika viruses, is an entry factor for SARS-CoV-2 to kidney cells, where the virus induces organ abnormalities associated with poor prognosis and mortality in COVID-19 patients." (PMID 36818472, 2022).
glomerulosclerosis (21 papers, 2014 to 2025). A hardening of the kidney glomerulus caused by scarring of the blood vessels. "Previous studies have shown that HAVCR1 is one of the key factors in renal tubular injury, PT cell cycle arrest, and secondary glomerulosclerosis." (PMID 38978780, 2024).
Obesity (17 papers, 2016 to 2026). Accumulation of substantial excess body fat. "Elevated HAVCR1 expression was associated with higher tumor grade, advanced stage, and obesity." (PMID 40928391, 2026).
renal cell carcinoma (17 papers, 2013 to 2025). "The HAVCR1 protein is also a useful biomarker for diagnosing renal cell carcinoma and ovarian clear-cell carcinoma." (PMID 37175405, 2023). "This HAVcR-1 ectodomain can be secreted into urine from certain tissue types, and this release is increased in renal cell carcinoma." (PMID 35204839, 2022). "Moreover, emerging evidence suggested that HAVCR1 was correlated with some aggressive tumors such as renal cell carcinoma, human colorectal cancer, and ovarian clear cell carcinoma." (PMID 31885544, 2019). "What's more, HAVCR1 overexpression was observed in renal cell carcinoma, human colorectal cancer, and ovarian clear cell carcinoma, which could promote the development and progression of tumors." (PMID 31885544, 2019). "HAVCR1 also known as T-cell immunoglobulin mucin domains (TIM)-1, is overexpressed in renal cell carcinoma, human colorectal cancer, and gastric adenocarcinomas, promoting the occurrence and progression of tumors." (PMID 35982956, 2022). "HAVcR-1 overexpression has previously been observed in breast cancer, ovarian cancer and renal cell carcinoma; therefore, providing further evidence that HAVcR-1 is not specific to a certain cancer type." (PMID 35204839, 2022).
IgA nephropathy (10 papers, 2013 to 2024). "The leakage of HAVCR1 and LCN2 into urine could be detected in IgA nephropathy." (PMID 26317775, 2015).
Lupus (10 papers, 2017 to 2025). "HAVCR1 has been reported to be associated with many diseases such as kidney injury, infection (hepatitis C virus, hepatitis A virus, and ebolavirus), and autoimmune diseases (allergy, asthma, and systemic lupus erythematosus patients)." (PMID 31885544, 2019).
gastric cancer (9 papers, 2018 to 2025). A primary or metastatic malignant neoplasm involving the stomach. "Our study further demonstrates that HAVCR1 is highly expressed in early gastric cancer patients with lymph node metastasis." (PMID 40406257, 2025). "The shedding of HAVCR-1 in gastric cancer increases the expression of IL-6 in RCC and activates the IL-6/STAT-3/HIF-1α pathway." (PMID 38831760, 2024). "One study has confirmed that AL139002.1 sponged miR-490-3p and regulated the expression of Hepatitis A virus cellular receptor 1 (HAVCR1) in gastric cancer, contributing to the development of gastric cancer." (PMID 37696973, 2023). "HAVcr-1 knockdown reduces the activity of proliferation and colony formation, migration, and invasion of gastric cancer cells in vitro." (PMID 34603757, 2021). "Notably, preliminary experiments indicated that HAVCR1 protein expression showed significant differences in metastatic gastric cancer tissues, leading to its selection for further validation as a LNM marker." (PMID 40406257, 2025). "HAVCR-1 might be a different predictor of the prognosis for stomach cancer if TCGA-STAD data are analyzed using univariate and multivariate Cox regression models." (PMID 38831760, 2024). "HAVCR1 is an important role in renal regression and immunity and has been published could be an biomarker for the prognosis and diagnosis for pan-cancer and also can be used for prognosis for gastric cancer." (PMID 40465781, 2025). "Through the intersection of differentially expressed genes (DEGs) that are highly expressed in gastric cancer tissues with those DEGs highly expressed in early-stage (T1) gastric cancer tissues exhibiting LNM, and with prognostic genes, we identified two biomarkers: HAVCR1 and Claudin 6 (CLDN6)." (PMID 40406257, 2025).
viral infection (9 papers, 2020 to 2024). "A high polymorphism of the HAVcr-1 gene in primates is supposed by the investigators to be the result of evolutionary divergence of the mechanisms of adaptation to viral infections and allergic reactions in mammals." (PMID 34603757, 2021). "HAVCR1 plays a critical role in regulating immune cell activity, particularly regarding the host response to viral infection, while TIMD4 is a T-cell immunoglobulin involved in regulating T-cell proliferation and lymphotoxin signalling." (PMID 32872585, 2020). "Additionally, in cells with low ACE2 expression, viral infection can be enhanced by additional host factors, such as the extracellular protease BSG (also known as CD147), the transmembrane receptor NRP1, lectins, or HAVCR1 phosphatidylserine receptors such TIM-1 (also known as TIMELESS) and AXL." (PMID 37458167, 2023).
asthma (8 papers, 2008 to 2024). "In African Americans, who predominantly carry the long-HAVCR1 allele (64% of the population), short-HAVCR1 was associated with protection against asthma independently of the HAV infection status." (PMID 39595207, 2024). "Hepatitis A virus cellular receptor 1 (HAVCR-1) is mainly a susceptibility gene for asthma and allergies, which is principally expressed on Th2 cells and acts as an effective costimulatory molecule for T cell activation." (PMID 34323652, 2021). "HAVCR1 is a costimulatory receptor in T cells and has been implicated as an asthma determinant." (PMID 19860892, 2009). "HAVCR1 has been reported to be involved in the allergic response, asthma, and the reduction in cell tight junction integrity." (PMID 37296766, 2023). "HAV infection has a protective effect in the development of allergy and asthma but the role of HAVCR1 in this protective affect is not well understood and will require a detailed analysis of the virus-receptor interaction." (PMID 19860892, 2009). "In addition to its role in viral defense, HAVCR1 is a key player in the hygiene hypothesis explaining the increase in allergies and asthma." (PMID 18670650, 2008).
kidney stone (8 papers, 2016 to 2025). "Therefore, C3, C5 and HAVCR1 related promotion of M2-like macrophage polarization and inhibition of inflammation could prevent intrarenal CaOx deposits, nucleation and kidney stone recurrence." (PMID 36932340, 2023).
renal carcinoma (8 papers, 2019 to 2025). A carcinoma arising from the epithelium of the renal parenchyma or the renal pelvis. "For colon cancer, identified biomarkers are CD15, CD104, CD324, CD326, CD49f, and for renal cancer, CD24, CD26, CD106 (VCAM1), EGFR, SSEA-3 (B3GALT5), SSEA-4 (TMCC1), TIM1 (HAVCR1), and TRA-1-60R (PODXL)." (PMID 36221114, 2022).
allergic disease (7 papers, 2008 to 2022). An immune response that occurs following re-exposure to an innocuous antigen, and that requires the presence of existing antibodies against that antigen. "Variability in HAVCR1 previously has been associated with susceptibility to allergic diseases, and also may be associated with susceptibility to infectious diseases." (PMID 21412435, 2011). "The aberrant expression of HAVCR1 (also known as KIM1) was first documented in kidney injury, then in autoimmune and allergic diseases." (PMID 35754803, 2022).
autoimmune disease (7 papers, 2014 to 2025). A disorder resulting from loss of function or tissue destruction of an organ or multiple organs, arising from humoral or cellular immune responses of the individual to their own tissue constituents. "These haplotype data in RA patients indicate that the mRNA level, in addition to ins/del in exon 4, is responsible for the association of HAVCR1 with RA, and suggest that long-HAVCR1 is protective against autoimmune diseases." (PMID 39595207, 2024).
atherosclerosis (6 papers, 2018 to 2025). A disease characterized by the build-up of fatty material and calcium deposition in the arterial wall resulting in partial or complete occlusion of the arterial lumen. "Blockade of TIMD4 and HAVCR1 enhanced the risk of atherosclerosis in LDL receptor-deficient mice." (PMID 29208769, 2018).